FPR1 (formyl peptide receptor 1)
Diseases named in the same sentence as FPR1 in open-access papers (continued):
Sharing a sentence is not in itself a finding about the gene and the disease.
FPR1 also shares sentences with these, for which no sentence is quoted: diabetes (4 papers); leukemia (4); acne (3); heart failure (3); infectious disease (3); influenza (3); neurodegenerative disease (3); staphylococcus aureus infection (3); ulcerative colitis (3); bladder cancer (2); chondrosarcoma (2); chronic granulomatous disease (2); chronic myelogenous leukaemia (2); epidermoid carcinoma (2); hepatocellular carcinoma (2); juvenile periodontitis (2); lung disease (2); metastatic melanoma (2); parasite infection (2); pneumococcal pneumonia (2); prion disease (2); acute leukemia (1); acute liver failure (1); acute lung injury (1); acute myeloid leukemia (1); acute myocardial infarction (1); Adrenal insufficiency (1); Airway obstruction (1); amyloidosis (1); amyotrophic lateral sclerosis (1).
A further 68 diseases each share a sentence with FPR1 in 1 paper.